WFDC2 (WAP four-disulfide core domain 2)
Diseases named in the same sentence as WFDC2 in open-access papers (continued):
Sharing a sentence is not in itself a finding about the gene and the disease.
prostate carcinoma (10 papers, 2013 to 2025). A carcinoma that arises from epithelial cells of the prostate gland. "Here, we first screened the diagnostic marker and favorable prognostic factor WFDC2 in prostate cancer by bioinformatics." (PMID 32678075, 2020). "Conversely, prostate cancer specimens often show significant downregulation of WFDC2, correlating inversely with Gleason grade parameters." (PMID 40350979, 2025). "Currently, WFDC protein family members, including WFDC1 and WFDC2, have been studied in relation to prostate cancer." (PMID 39296934, 2024). "At the same time, WFDC2 also inhibits epithelial-mesenchymal transition in prostate cancer through inactivating EGFR signaling." (PMID 39296934, 2024). "For example, WFDC1 is highly expressed in prostate cancer, and WFDC2 shows abnormal expression in various tumor cells." (PMID 39296934, 2024). "After validation by database and tissue microarray, we found that WFDC2 was dramatically downregulated in human prostate cancer and negatively correlated with Gleason score." (PMID 32678075, 2020). "After demonstrating that WFDC2 inhibits the metastatic ability of prostate cancer by binding to the EGFR extracellular domain, we overexpressed WFDC2 and EGFR in PC-3 and DU-145 simultaneously." (PMID 32678075, 2020). "In conclusion, our study identified that the tumor suppressor WFDC2 can suppress prostate cancer metastasis by inactivating EGFR signaling." (PMID 32678075, 2020). "We also uncovered that WFDC2 is an independent and favorable prognostic factor of human prostate cancer." (PMID 32678075, 2020). "In our study, we identified that the tumor suppressor WFDC2 can obviously inhibit the metastasis of prostate cancer in vitro and in vivo." (PMID 32678075, 2020). "On the other hand, WFDC2 has been identified as a prominent biomarker in various cancers, including lung, ovarian, and prostate cancers, with roles in tumor metastasis and prognosis due to its interaction with EGFR and its ability to modulate cancer cell migration." (PMID 39296934, 2024). "WFDC2, which may serve as a potential clinical treatment target of PCa, suppressed prostate cancer metastasis by inactivating EGFR signaling." (PMID 32678075, 2020). "This raised our interest regarding the function of WFDC2 in prostate cancer." (PMID 32678075, 2020). "WFDC2 expression was negatively correlated with Gleason score and metastasis in prostate cancer." (PMID 32678075, 2020). "Therefore, we speculate that WFDC2 inhibits prostate cancer metastasis by inactivating EGFR signaling." (PMID 32678075, 2020). "WFDC2 inhibits EGFR activation by binding to its extracellular domain, thus inhibiting prostate cancer metastasis." (PMID 39296934, 2024). "Then, we revealed that overexpression of WFDC2, and addition of recombinant protein HE4 can significantly inhibit prostate cancer metastasis in vivo and in vitro." (PMID 32678075, 2020). "To further validate the specific interaction domain between WFDC2 and EGFR in prostate cancer, we divided EGFR into the extracellular domain EGFR-NT and the intracellular domain EGFR-NT." (PMID 32678075, 2020). "Therefore, we speculated that WFDC2 may be negatively correlated with prostate cancer metastasis." (PMID 32678075, 2020). "WFDC2 exhibits the capability to inhibit the metastasis of PC by blocking the activation of EGFR, suggesting that WFDC2 may be a promising therapeutic target for prostate cancer." (PMID 39296934, 2024). "WFDC2 was strongly upregulated in normal prostate tissues and could not be detected in prostate cancers." (PMID 32678075, 2020). "However, the specific function of WFDC2 in prostate cancer has not been reported." (PMID 32678075, 2020).
endometrioid ovarian cancer (9 papers, 2009 to 2024). "Human epididymis protein 4 (HE4), encoded by the gene WFDC2, is a secreted glycoprotein that is overexpressed in serous and endometrioid ovarian cancers." (PMID 33036656, 2020). "HE4, WFDC2, is overexpressed in Endometrioid ovarian cancer and less in epithelial tissues of the respiratory system and reproductive organs." (PMID 37238188, 2023).
gastric cancer (9 papers, 2015 to 2025). A primary or metastatic malignant neoplasm involving the stomach. "Hypoxia-induced upregulation of WFDC2 has been implicated in radiation therapy resistance in gastric cancer, with similar effects observed in colorectal cancer, where WFDC2 expression reduces radiation sensitivity." (PMID 40727473, 2025). "Recent studies have highlighted that WFDC2 is overexpressed in gastric cancer, where it is linked to poor prognosis and resistance to radiation therapy." (PMID 40727473, 2025). "WFDC2 expression was significantly higher in gastric cancer, LUAD, esophageal carcinoma, and pancreatic ductal adenocarcinoma (PDAC) tumor tissues than in normal tissues (p < 0.01)." (PMID 40727473, 2025). "In gastric cancer, univariate analysis revealed that WFDC2 concentration (HR = 1.04, 95% CI: 1.01–1.07, p = 0.005) and PS (HR = 2.46, 95% CI: 1.02–5.90, p = 0.044) were significantly associated with OS." (PMID 40727473, 2025). "In contrast, WFDC2 mRNA expression levels were not significantly correlated with OS in gastric cancer, rectal adenocarcinoma, ESAD, ESCC, or PDAC (p > 0.05 for all comparisons)." (PMID 40727473, 2025).
diabetes (8 papers, 2015 to 2025). "Another study also showed that serum WFDC2 is associated with renal function and DKD in patients with type 2 diabetes mellitus." (PMID 33644086, 2020). "Here, in this study, our data showed that WFDC2 was upregulated in the tubules causing PEX19 expression to decrease in the glomeruli, which provide a new mechanism of how WFDC2 regulates diabetes and DKD." (PMID 33644086, 2020).
endometrioid carcinomas (8 papers, 2015 to 2025). "Human epididymis protein 4 (HE4), encoded by WFDC2, is a highly specific OC biomarker, expressed in most serous and endometrioid carcinomas but not in normal ovarian tissue." (PMID 40927964, 2025).
renal dysfunction (8 papers, 2017 to 2025). "Furthermore, WFDC2 levels can be influenced by renal dysfunction and smoking, as shown in previous reports." (PMID 40723266, 2025).
COVID-19 (6 papers, 2020 to 2023). A disease caused by infection with severe acute respiratory syndrome coronavirus 2. "The common plasma proteins that were higher in the COVID-19 patients than controls and that were higher in the late recovery group than the early recovery group for phases 1 and 2 were WFDC2, CHI3L1, GDF15, KRT19, and TNFRSF10B." (PMID 36331721, 2023). "In our study, the critical COVID-19 patients were divided into three phenotypes (α, β, γ) using WFDC2, CHI3L1, and KRT19 on day 1 by latent class analysis." (PMID 36331721, 2023). "We thus concluded that WFDC2, GDF15, CHI3L1, and KRT19 were four key proteins related to COVID-19 severity." (PMID 36331721, 2023). "In the present study, GDF15, WFDC2, and CHI3LI were correlated with age in the COVID-19 patients." (PMID 36331721, 2023).
squamous cell carcinoma (6 papers, 2022 to 2025). A carcinoma arising from squamous epithelial cells. "Overall, WFDC2 expression varied across different cancer types, exhibiting distinct patterns between adenocarcinomas and squamous cell carcinomas, as well as between gastrointestinal malignancies." (PMID 40727473, 2025). "WFDC2 protein is elevated in malignant pleural effusion and has diagnostic value in LUAD, squamous cell carcinoma, and small cell carcinoma." (PMID 36721112, 2023).
interstitial lung disease (5 papers, 2021 to 2024). A diverse group of lung diseases that affect the lung parenchyma. "This agrees with previous reports in individuals with CF and recent studies reporting increased WFDC2 expression in interstitial lung disease." (PMID 38626355, 2024). "Candidate biomarkers CXCL9, GDF15, and vWF have previously been shown to correlate with global JDM activity, and WFDC2 and TNFSF13 have been associated with interstitial lung disease in DM." (PMID 39529136, 2024).
Lung Disease (5 papers, 2006 to 2025). "Potentially; levels of WFDC2 in CF lung secretions may influence the development of lung disease in this condition." (PMID 16600032, 2006).
Pleural effusion (5 papers, 2015 to 2026). The presence of an excessive amount of fluid in the pleural cavity. "We also identified pleural effusion predictive gene signatures, including TMPRSS3, MS4A7, NAPSA, and IGFBP2, while liver metastasis predictive markers included WFDC2, HSPB1, COX6C, APOE, and TUBA1A." (PMID 39955556, 2025).
colon cancer (4 papers, 2021 to 2025). "In contrast, WFDC2 expression was significantly lower in colon cancer and rectal cancer tumor tissues than in their corresponding normal tissues (p < 0.005)." (PMID 40727473, 2025).
colorectal cancer (4 papers, 2019 to 2025). A primary or metastatic malignant neoplasm that affects the colon or rectum. "In contrast, WFDC2 expression was significantly lower in colorectal cancer, suggesting an inverse correlation between WFDC2 expression and cancer progression in some gastrointestinal cancer tissues." (PMID 40727473, 2025). "This contrasts with database analyses showing lower WFDC2 mRNA expression in colorectal cancer tissue than in normal tissue, despite elevated plasma WFDC2 concentrations in patients." (PMID 40727473, 2025). "This suggests that WFDC2 is secreted into the bloodstream at lower levels from colorectal cancer tissue than from other cancer types." (PMID 40727473, 2025).
fibrosis (4 papers, 2016 to 2025). the formation of excess fibrous connective tissue in an organ or tissue in a reparative or reactive process. "WFDC2, also known as HE4, is an anti-protease that promotes angiogenesis and is associated with kidney and lung fibrosis." (PMID 36572854, 2022).
diabetic kidney disease (3 papers, 2019 to 2023). Progressive kidney disorder caused by vascular damage to the glomerular capillaries, in patients with diabetes mellitus. "Secreted protein comparison and verification experiments indicated that WFDC2 from the tubule could downregulate PEX19 mRNA and protein levels at the glomeruli in diabetic kidney disease (DKD)." (PMID 33644086, 2020). "Western blotting and immunohistochemical staining results showed that Wfdc2 expression in the urine and kidneys of DKD patients was higher than that in non-diabetic kidney disease (NDKD) controls." (PMID 37827693, 2023).
nasal polyps (3 papers, 2006 to 2024). "Here, we describe a novel Mendelian disorder of chronic destructive airway disease characterized by bronchiectasis, chronic infection of the airways, pronounced CRS, and nasal polyposis due to autosomal recessive inheritance of pathogenic WFDC2 variants." (PMID 38626355, 2024). "In the NP (eCRSwNP and neCRSwNP) groups, WFDC2 was expressed in individual cells in the mucosal epithelium of nasal polyps." (PMID 38280891, 2024). "In the UT (eCRSwNP and neCRSwNP) groups, WFDC2 was presented scattered expression in the mucosa epithelium adjacent to nasal polyps." (PMID 38280891, 2024). "We stained nasal polyps from >15 individuals all of which demonstrated WFDC2 in ductular cells of the minor mucous glands, although the intensity of staining varied and some regions of individual glands were found to be negative." (PMID 16600032, 2006). "In the light of our previous observation that significant expression of WFDC2 RNA was seen in tissue from the nasal passages, we initially stained sections from the maxillary sinus (antral) mucosa and nasal polyps." (PMID 16600032, 2006). "The results have revealed the key cell subsets that may be involved in forming nasal polyps and nasal mucosa inflammation and identified WFDC2 and CCL26 as the key genes involved in developing CRSwNP." (PMID 38280891, 2024).
Sepsis (3 papers, 2022 to 2023). Sepsis is defined as life-threatening organ dysfunction caused by a dysregulated host response to infection. "Moreover, transcriptional differences between Native Hawaiians and Japanese CRC-S patients suggest early and late responses are significantly altered in sepsis progression, which may be reflected in the potential biomarkers we identified such as GSK3B, WFDC2 and MTRNR2L1." (PMID 36450776, 2022).
allergic rhinitis (2 papers, 2021 to 2024). Inflammation of the nasal mucous membranes caused by an IgE-mediated response to external allergens. "Like Jchain, Wfdc2 was shown to be decreased in the nasal mucosa of individuals with allergic rhinitis as compared to healthy controls." (PMID 34464420, 2021).
esophageal cancer (2 papers, 2023 to 2025). A primary or metastatic malignant neoplasm involving the esophagus. "Plasma WFDC2 levels demonstrated potential diagnostic performance across multiple cancers and were significantly associated with poor prognosis in gastric and esophageal cancers." (PMID 40727473, 2025). "Kaplan-Meier survival analysis was performed to assess the association between plasma WFDC2 expression levels and OS in patients with gastric, lung, colorectal, and esophageal cancer." (PMID 40727473, 2025). "Elevated plasma WFDC2 levels were significantly associated with shorter OS in esophageal cancer (p = 0.0226)." (PMID 40727473, 2025). "Plasma WFDC2 levels were significantly elevated in patients with cancer, indicating potential diagnostic utility across various cancers, including gastric, lung, colorectal, and esophageal cancers." (PMID 40727473, 2025). "Thus, WFDC2 concentration was identified as being independently associated with poor prognosis in both gastric and esophageal cancers based on multivariate analysis." (PMID 40727473, 2025). "Furthermore, elevated WFDC2 levels were associated with poor prognosis in gastric and esophageal cancers, highlighting its value as a prognostic biomarker." (PMID 40727473, 2025). "Multivariate Cox regression analysis confirmed that plasma WFDC2 concentration was an independent prognostic factor in gastric (HR = 1.04, 95% CI: 1.00–1.07, p = 0.019) and esophageal cancers (HR = 1.08, 95% CI: 1.02–1.13, p = 0.006)." (PMID 40727473, 2025). "We have demonstrated that WFDC2 serves as a prognostic factor in esophageal cancer, which is a key finding." (PMID 40727473, 2025). "In colorectal and esophageal cancer, serum WFDC2 levels have been proposed as a potential biomarker; however, their diagnostic capability remains limited and insufficient for clinical application." (PMID 40727473, 2025).
large cell carcinoma (2 papers, 2006 to 2022). A malignant epithelial neoplasm composed of large, atypical cells. "This study also clearly shows that WFDC2 expression is not purely associated with this tumour type as a significant percentage (20–30%) of other tumour types, for example squamous, small and large cell carcinomas, also exhibited focal positive staining for the protein." (PMID 16600032, 2006).
respiratory failure (2 papers, 2019 to 2024). The significant impairment of gas exchange within the lungs resulting in hypoxia, hypercarbia, or both, to the extent that organ tissue perfusion is severely compromised. "Mouse models deficient for WFDC2 exhibit respiratory failure and die in the neonatal period: defects include apoptosis of type-1 alveolar cells and thickening of the alveolar interstitium and shortened cilia and impaired alveolar type-II function." (PMID 38626355, 2024). "We show here that deleting Wfdc2 in mice causes perinatal death due to respiratory failure soon after birth." (PMID 31562139, 2019). "Given that the reduction of PC concentration increases the surface tension, a decrease in PC may be linked to progressive atelectasis and respiratory failure in Wfdc2-deficient mice." (PMID 31562139, 2019). "In the lung, since Wfdc2 is induced after birth and plays crucial roles in preventing atelectasis and possibly maintaining the barrier function, the decrease in WFDC2 expression might be a factor in human respiratory failure, an issue that should be addressed in future studies." (PMID 31562139, 2019).
bladder cancer (1 paper, 2024). "PVRL4 was predominantly expressed in BC epithelial cells, AREG was expressed in BC epithelial cells and normal control myeloid cells, and FGFBP1 and WFDC2 were expressed in bladder cancer epithelial cells but not in normal tissue." (PMID 38532419, 2024).
bronchiectasis (1 paper, 2024). Segmental, irreversible dilation of the bronchial tree resulting in the accumulation of secretions which leads to obstruction. "Several groups identified ultrarare and pathogenic WFDC2 variants in individuals with bronchiectasis and connected through GeneMatcher." (PMID 38626355, 2024). "WFDC2 dysfunction defines a novel molecular etiology of bronchiectasis characterized by the deficiency of a secreted component of the airways." (PMID 38626355, 2024). "All individuals with biallelic WFDC2 variants presented with marked chronic respiratory symptoms affecting the upper and lower airways, and 9 of 11 individuals showed bronchiectasis by CT imaging." (PMID 38626355, 2024). "Furthermore, nine individuals with WFDC2 mutations suffered from chronic P. aeruginosa infection, which is known to be a risk factor associated with bronchiectasis." (PMID 38626355, 2024).
chronic lung disease (1 paper, 2025). According to the definitions of the American and British Thoracic Societies, including pulmonary functional tests, X-rays, and CT scans for items such as fibrosis, bronchiectasis, bullae, emphysema, nodular or lymphomatous abnormalities. "Finally, the plasma levels of GDF15 and WFDC2 were measured due to their previous association with damage in several chronic lung diseases." (PMID 40247373, 2025). "Finally, PS patients showed increased levels of GDF15 and WFDC2, both mediators of epithelial damage, associated with lung alterations and chronic lung diseases." (PMID 40247373, 2025).
colitis (1 paper, 2022). Inflammation of the colon. "Thus ERS-induced mucin depletion seems to be a relevant pathogenetic mechanism of colitis in IL-10 deficient mice; our results demonstrating a significantly reduced number of goblet cells and expression of MUC-2, IL-18, WFDC2 and Xbp-1 in IL-10 deficient mice at young ages support this hypothesis." (PMID 36699599, 2022).
corneal disease (1 paper, 2024). "Here, we report that WFDC2 and GPRC5A expression may be a novel marker for the corneal epithelial cells and subsequent EVs, but their functional role has yet to be determined, with WFDC2 and GPRC5A reported only in non-corneal disease models." (PMID 39408670, 2024).
inflammatory bowel disease (1 paper, 2019). A spectrum of small and large bowel inflammatory diseases of unknown etiology. "During the preparation of the manuscript, a new report was published showing that human WFDC2 is downregulated in goblet cells in inflammatory bowel disease (IBD) patients and participates in the pathogenesis of IBD." (PMID 31562139, 2019).
liver dysfunction (1 paper, 2010). "Although physiological significance of WFDC2 in the liver has yet to be identified and dogs used in this experiment were all clinically healthy, it may be worthy to study this gene as a potential biomarker for the progression of liver dysfunction." (PMID 20967283, 2010).
nasopharyngeal carcinoma (1 paper, 2021). A carcinoma arising from the nasopharyngeal epithelium. "In addition, consistent with the expression of CAPS and WFDC2 in nasopharyngeal carcinoma, Kaplan Meier’s survival analysis exhibited the remarkable prolongation of the overall survival periods in the patients with low CAPS and WFDC2." (PMID 33790390, 2021).
ulcerative colitis (1 paper, 2022). An inflammatory bowel disease involving the mucosal surface of the large intestine and rectum. "WFDC2 was found to be downregulated in human ulcerative colitis (UC) colonic samples compared to healthy patients, and Wfdc2+/− mice show abnormalities in colonic epithelial intercellular junctions." (PMID 35100877, 2022).